CD4 (CD4 molecule)
Diseases named in the same sentence as CD4 in open-access papers (continued):
Sharing a sentence is not in itself a finding about the gene and the disease.
colon carcinoma (continued). "The histogram and the heat map could indicate that T cells CD4 memory resting, T cells CD8, Macrophages M0 and Macrophages M2 were obviously tested high-expression in primary tumor and distance metastasis tissues, and they might play essential roles in colon cancer." (PMID 32850813, 2020). "In primary colon cancer, the expression of CD69, an indicator of CD4+ T-cell activation, was not significantly affected by αPD-1 or Re-FMT." (PMID 40191185, 2025). "The infiltration of CD4, CD8, and CD163 in tumor tissues after CXCL1 knockout was not significantly different from that in wild-type colon cancer tissues." (PMID 36434686, 2022). "For C3 (CD4+ TEMRA/TEFF), only three DEGs were screened between colon cancer and rectal cancer, and no DEGs were found for C6 (CD8+TCM)." (PMID 33584715, 2020). "Treatment of CD4 CD8 double-negative T-cells, T-cell leukemia, diffuse large B cell lymphoma and colon cancer cell lines for 4–48 hours with 300–15000 nM Galectin-3 was reported to result in apoptosis of the recipient cells." (PMID 25869099, 2015). "In C26-colon-carcinoma bearing BALB/c mice, we found an increase of CD4+CD25+/CD4+ in spleen but not in peripheral blood, furthermore, the proportion in spleen lymphocytes increased with the increase of tumor sizes." (PMID 15679891, 2005).
experimental autoimmune encephalomyelitis (240 papers, 2011 to 2026). An autoimmune demyelinating disease of the central nervous system that is produced experimentally in animals by the injection of homogenized brain or spinal cord in Freund's adjuvant. "The findings reveal that Fak deficiency in CD4 T cells significantly reduces Th17 differentiation, while also promoting regulatory T (Treg) cell differentiation, thereby ameliorating symptoms of experimental autoimmune encephalomyelitis (EAE)." (PMID 41050684, 2025). "In our previous work, accumulated DNA in CD4+ T cells promoted proliferation and pathogenic phenotypes in experimental autoimmune encephalomyelitis (EAE)." (PMID 39872301, 2023). "AP-ctCTLA-4 reduced IL-17A expression under Th17 differentiation conditions in vitro and ameliorated experimental autoimmune encephalomyelitis, with decreased numbers of pathogenic IL-17A+GM-CSF+ CD4 T cells." (PMID 34452095, 2021). "Both CD4+ T cell-specific conditional p19-deficient mice and complete CD5L-deficient mice showed significantly alleviated experimental autoimmune encephalomyelitis (EAE) with reduced frequency of GM-CSF+CD4+ T cells." (PMID 33664371, 2021). "Specifically, loss of STAT5 in CD4+ T cells resulted in decreased development of experimental autoimmune encephalomyelitis (EAE), a mouse model of MS, relative to WT CD4+ T cells that produce GM-CSF normally." (PMID 31813764, 2020). "Casz1 deficiency in CD4+ T cells lowers susceptibility to experimental autoimmune encephalomyelitis, consistent with the reduced frequency of Th17 cells, despite an increase in Th1 cells in mice." (PMID 29467767, 2018). "To understand the effects driven by Th17 cells in the CNS, we induced experimental autoimmune encephalomyelitis in wild-type mice and CD4+ T cell-specific integrin α4-deficient mice where trafficking of Th1 cells into the CNS was affected." (PMID 29037246, 2017). "Using this model, we show that Vav1R63W mice display reduced susceptibility to experimental autoimmune encephalomyelitis associated with a lower production of effector cytokines by autoreactive CD4 T cells that is intrinsic to effector CD4 T cells." (PMID 27438086, 2016). "Furthermore, this group reconstituted wild-type (WT) and GPR65-knockout (KO) CD4+ T cells into RAG-deficient mice and observed the loss of GPR65 in CD4+ T cells protected mice from experimental autoimmune encephalomyelitis (EAE)." (PMID 39336742, 2024). "Likewise, in experimental autoimmune encephalomyelitis the pathogenic inflammation seems to be caused by GM-CSF producing CD4 T cells upon neuroantigen recognition on moDC/macrophages associated with vessels of the central nervous system." (PMID 35903540, 2022). "Using a Vav1R63W knock-in mouse model, we show that Vav1R63W leads to defects in adaptor functions and reduces the susceptibility to experimental autoimmune encephalomyelitis, together with an intrinsic defect in the production of Th1/Th17 cytokines by autoreactive effector CD4 T cells." (PMID 27438086, 2016). "It had been implicated that CXCR3 is highly expressed on pro-inflammatory human CD4+Th17 cells, “pathogenic” human Th1/17 cells, and myelin oligodendrocyte glycoprotein-specific CD4+ T cells in experimental autoimmune encephalomyelitis mice in combination with other biomarkers." (PMID 26150899, 2015). "The ability of myelin-reactive CD4 T cells to cause experimental autoimmune encephalomyelitis (EAE) further supports the hypothesis that myelin-reactive CD4 T cells have a central role in MS disease pathogenesis." (PMID 26300731, 2015). "We then tested whether the Qa-1-restricted CD8+ T cells induced upon the first CD4+ T cell response could control a second CD4+ T cell response implicated in the pathogenesis of murine experimental autoimmune encephalomyelitis (EAE)." (PMID 21738737, 2011).
experimental autoimmune encephalomyelitis (continued). "It has been shown that leptin-deficient mice were resistant to experimental autoimmune encephalomyelitis, an animal model of human MS and that this adipokine can affect the survival and proliferation of autoreactive CD4(+) T cells in experimental autoimmune encephalomyelitis." (PMID 21935388, 2011). "In a previous study on JM4 in experimental autoimmune encephalomyelitis, we demonstrated that this treatment blocked dendritic cell proliferation and this was associated with a decrease in Th17 cells, proinflammatory cytokines, and increase in CD4 FoxP3 Treg cells." (PMID 31572168, 2019). "This is also the case for autoreactive 2D2 TCR transgenic T cells, a widely employed mouse model in studying the pathogenesis of CD4 T cell-mediated experimental autoimmune encephalomyelitis." (PMID 40681578, 2025). "To induce this identity in proinflammatory CD4+ Teff cells from mice with experimental autoimmune encephalomyelitis (EAE), we first optimized conditions for efficient Foxp3 induction." (PMID 40762956, 2025). "Consistent with our in vitro data, genetic ablation of Caveolin-1 reduces infiltration of CXCR3+ CD4+ T cells into the CNS in experimental autoimmune encephalomyelitis." (PMID 40063988, 2025). "In this context, we demonstrated that the selective ablation of early growth response gene 1 (Egr-1) in CD4+ T cells exacerbated experimental autoimmune encephalomyelitis (EAE) in murine models." (PMID 40235598, 2025). "We used the experimental autoimmune encephalomyelitis (EAE) disease model since PD-1+ CD4 T cells are found in high numbers in the brains and spinal cords of EAE mice." (PMID 40881711, 2025). "In another study, PPARα-KO mice presented increased IL-17A+CD4+ T-cell (Th17) generation, resulting in increased pathological features of murine experimental autoimmune encephalomyelitis (EAE)." (PMID 39910334, 2025). "In the model of experimental autoimmune encephalomyelitis (EAE), a mouse analog for MS, such an upregulation of chemokines, facilitates the incursion of CNS-reactive CD4 + T cells (deemed pathogenic CD4 + T cells) through the L5 dorsal vessels." (PMID 38449060, 2024). "In a mouse model of experimental autoimmune encephalomyelitis, bilirubin mediated its immune response to CD4+ T cell reactivity via inhibition of its costimulatory activity and immune transcription factor activation." (PMID 38313187, 2024). "The ability of CD4 T cells to transfer demyelinating disease in murine experimental autoimmune encephalomyelitis (EAE) confirms that T cell recognition of myelin epitopes is sufficient to initiate paralysis." (PMID 39330967, 2024). "Btn2a2-deficient mice showed enhanced effector CD4+ and CD8+ T cell responses, impaired CD4+ regulatory T cell induction, potentiated antitumor responses, and exacerbated experimental autoimmune encephalomyelitis." (PMID 38571951, 2024). "In another study, PPARα-KO mice showed increased helper CD4+ T cell type 17 (Th17) generation resulting in increased pathology of murine experimental autoimmune encephalomyelitis." (PMID 38746124, 2024). "We identified that Bhlhe40 in CCR6high MP CD4+ T cells as a key regulator of GM-CSF expression through IL-23 and IL-1β signaling, contributing to central nervous system (CNS) pathology in experimental autoimmune encephalomyelitis." (PMID 37121980, 2023). "In an autoimmune context, DKK3 produced locally by stromal cells in the skin was found to reduce self-antigen–induced experimental autoimmune encephalomyelitis symptoms in a CD4+ T cell–dependent fashion." (PMID 37847565, 2023). "Autoreactive CD4+ T cells from peripheral lymphoid organs or CD4+ T cells activated by central nervous system (CNS) local antigen play a crucial role in the pathogenesis of MS and its animal model, experimental autoimmune encephalomyelitis (EAE)." (PMID 37187757, 2023).
experimental autoimmune encephalomyelitis (continued). "Hereby, Pik3c3f/f;CD4-Cre mice proved to be resistant to experimental autoimmune encephalomyelitis, highlighting the possibility to target CD4+ T cell differentiation for the treatment of inflammatory diseases." (PMID 38071322, 2023). "To focus on potential pericyte—CD4+ T cell interactions during T cell entry into the CNS and exclude peripheral T cell priming effects, we made use of the adoptive transfer model of experimental autoimmune encephalomyelitis (AT-EAE)." (PMID 36361868, 2022). "NK cell depletion can lead to the enhanced development of experimental autoimmune encephalomyelitis (EAE) due to increased numbers of auto-reactive CD4+ T cells." (PMID 35172900, 2022). "Studies have uncovered the crucial role that RGC-32 plays in promoting the differentiation of Th17 cells, a subtype of CD4+ T lymphocytes with an important role in MS and its murine model, experimental autoimmune encephalomyelitis." (PMID 36172382, 2022). "Expansion in vitro of myelin basic protein (MBP)-reactive CD4+CD25+ Tregs from donor TCR transgenic mice was able to protect from experimental autoimmune encephalomyelitis." (PMID 35740942, 2022). "As with ORAI1, experimental autoimmune encephalomyelitis was ameliorated by inhibition of Kv1.3 alone, or of both Kv1.3 and KCa3.1, in CD4+ T-lymphocytes." (PMID 34639190, 2021). "To identify GPCRs involved in T cell regulation during neuroinflammation, we determined GPCR expression in naïve and spinal cord-infiltrating CD4 T cells during experimental autoimmune encephalomyelitis (EAE), a mouse model of MS." (PMID 34815397, 2021). "Previous studies have shown that pharmacological activation of PKM2 inhibits CD4+ T cell pathogenicity and suppresses experimental autoimmune encephalomyelitis." (PMID 34645459, 2021). "Nevertheless, IFN-γ stimulates differentiation of CD4+CD25– T-cells in CD4+ Tregs in a mouse model of experimental autoimmune encephalomyelitis as well inhibiting the proliferation of Th2 cells." (PMID 32582698, 2020). "NKG2A on NK cells prevents NK cell killing of Qa-1-expressing pathogenic CD4+ T cells in experimental autoimmune encephalomyelitis, suggesting that inhibition of NKG2A-Qa-1 interaction suppresses CD4+ T cell responses to autoantigens." (PMID 32403291, 2020). "The changes of TLR4 in CD4+ T cells from MS patients and experimental autoimmune encephalomyelitis (EAE) mice were tested." (PMID 31561751, 2019). "The expression of TSPAN32 was assessed in CD4+ T cells from a model of experimental autoimmune encephalomyelitis (EAE)." (PMID 31487788, 2019). "For example, we have shown that human CRP inhibits the progression of experimental autoimmune encephalomyelitis (EAE) in CRP transgenic mice by shifting CD4+ T cells away from the TH1 and toward the TH2 subset." (PMID 29556231, 2018). "Traf5−/− donor CD4+ T cells exacerbate the development of neuroinflammation in experimental autoimmune encephalomyelitis (EAE) in wild-type recipient mice." (PMID 30214449, 2018). "CD4+ Th1 cells and CD4+ Th17 cells are the two subtypes of CD4+ T cells which have been intensively investigated in MS and its animal model, experimental autoimmune encephalomyelitis (EAE)." (PMID 29915595, 2018). "Meanwhile, inhibition of autophagy significantly improved the therapeutic effects of MSCs on experimental autoimmune encephalomyelitis by regulating the activation and expansion of CD4+ T cells." (PMID 30486857, 2018). "Previous studies in animal models of experimental autoimmune encephalomyelitis and myocarditis have shown that CD4+ T cells secreting GM-CSF were critical in their pathogenesis." (PMID 29375580, 2017). "To understand the role of ARMC5 in in vivo T-cell immune responses, particularly CD4-mediated immune responses, we induced experimental autoimmune encephalomyelitis (EAE) in Armc5 WT and KO mice." (PMID 28169274, 2017).
experimental autoimmune encephalomyelitis (continued). "Recently, we reported treatment targeting CD226 can ameliorate experimental autoimmune encephalomyelitis (EAE) by promoting IL‐10 expression via regulation of CD4+ T cell differentiation." (PMID 29299389, 2017). "In two studies on neonatal mice exposed to endotoxin inhalation and on mice with experimental autoimmune encephalomyelitis, respectively, an activated Th17 CD4 T cell population was found to be involved in inducing TLO structures." (PMID 27579026, 2016). "While some studies suggest a regulatory role of CD8 T lymphocytes on CD4 T cell activity and dendritic cell activation during experimental autoimmune encephalomyelitis (EAE), other demonstrate that CD8 T cells aggravate CD4 T cell mediated EAE." (PMID 27378849, 2016). "In a mouse model of MS, experimental autoimmune encephalomyelitis, guanabenz alleviates clinical symptoms, which correlates with increased oligodendrocyte survival and diminished CNS CD4+ T cell accumulation." (PMID 25766071, 2015). "Experimental autoimmune encephalomyelitis is characterized by infiltration of CD4+ and CD8+ cells into the CNS." (PMID 25762984, 2015). "Past studies have shown that CD4+ T cells play a critical role in the development of MS and experimental autoimmune encephalomyelitis (EAE), a widely used mouse model of MS." (PMID 25838639, 2015). "Experimental autoimmune encephalomyelitis (EAE) is a CD4+ T cell mediated inflammatory demyelinating disease that is induced in mice by administration of peptides derived from myelin proteins." (PMID 26580651, 2015). "Recently, using experimental autoimmune encephalomyelitis (EAE), an animal model of MS, we found a “gateway” at the fifth lumber cord where pathogenic autoreactive CD4+ T cells can cross the BBB." (PMID 23990699, 2013). "SnL are also upregulated on subsets of CD4+FoxP3+ regulatory T cells (Tregs) in experimental autoimmune encephalomyelitis (EAE), leading to an Sn-dependent reduction in numbers of Tregs and exacerbation of disease." (PMID 24286366, 2013). "Experimental autoimmune encephalomyelitis (EAE) depends on the initial activation of CD4+ T cells responsive to myelin autoantigens." (PMID 23111144, 2012). "Experimental autoimmune encephalomyelitis is a widely studied autoimmune model, and involves infiltration of CD4+ lymphocytes and immunological activation of microglia within the CNS." (PMID 21942980, 2011). "However, little is known about the role of CD8 T cells in MS, partly due to the prevalent use of experimental autoimmune encephalomyelitis (EAE) models mediated by CD4 T cells, which have limited involvement of CD8 T cells." (PMID 42171609, 2026). "The absence of CASZ1 in CD4+ T cells reduced susceptibility to experimental autoimmune encephalomyelitis." (PMID 40868317, 2025). "The CD28 PYAP ICD, which is necessary for ARS2 upregulation, was previously shown to be important for in vivo T-cell functions in models of allergic airway inflammation and experimental autoimmune encephalomyelitis, both of which are driven primarily by CD4+ T cells." (PMID 38233562, 2024). "In addition, CD4+ CTLs lose the expression of THPOK and gain the expression of T‐BET and RUNX3 in intraepithelial lymphocytes, whereas cytotoxic T‐cell‐like CD4+ T cells express EOMES in experimental autoimmune encephalomyelitis." (PMID 37829505, 2023). "Moreover, the role of CD73 in CD4+ T cells for the efficient entry into the central nervous system during the development of experimental autoimmune encephalomyelitis has been documented." (PMID 35325005, 2022). "Moreover, the expression of CD73 on CD4+ T cells is required for the efficient entry into the central nervous system in the experimental autoimmune encephalomyelitis (EAE) model." (PMID 35325005, 2022).